INS (insulin)
Diseases named in the same sentence as INS in open-access papers (continued):
Sharing a sentence is not in itself a finding about the gene and the disease.
Obesity (continued). "Genetic deletion of muscle SIRPα protected against obesity and improved intracellular insulin signaling in muscle and adipose tissue, with reduced intramuscular fat deposition when compared with flox mice on HFD." (PMID 41657313, 2026). "Reduced plasma mI concentrations have been reported in insulin-resistant states, including obesity and polycystic ovary syndrome, and mI supplementation has been shown to improve insulin sensitivity and metabolic parameters in these conditions." (PMID 41596611, 2026). "It exerts protective effects against obesity and related metabolic disorders through mechanisms such as improving insulin sensitivity, promoting lipid metabolism, and inhibiting inflammatory responses." (PMID 41503874, 2026). "This pattern is particularly evident in individuals with obesity, where excess adipose tissue acts as an endocrine organ, releasing pro-inflammatory cytokines that further impair insulin signaling." (PMID 40076739, 2025). "Under insulin-resistant conditions, such as obesity, pancreatic β cells adaptively proliferate and secrete more insulin to prevent blood glucose elevation." (PMID 40337860, 2025). "Magnesium and vitamin D correction not only improve bone mineral density but also enhance insulin sensitivity and vascular function, preventing secondary complications of obesity-induced electrolyte disturbances." (PMID 40136609, 2025). "Inflammatory cytokines such as TNF-α, IL-1β, and IL-6 can reduce insulin sensitivity and promote obesity." (PMID 40298814, 2025). "In this study, we investigate the effects of inhibiting 5-HT signaling on skeletal muscle insulin sensitivity in a mouse model of diet-induced obesity." (PMID 40451926, 2025). "Studies have shown that enhancing NO production can improve insulin sensitivity and reduce obesity-related complications." (PMID 41394126, 2025). "Studies have reported an increased prevalence of MetS, dyslipidemia, and PCOS and higher levels of fasting plasma glucose, insulin, and tryglycerides in patients suffering from HS, while obesity is recognized as an exacerbating factor." (PMID 40806666, 2025). "Previous studies have shown that AEA can modulate insulin sensitivity, inflammation, and endothelial function, all of which are relevant to the pathophysiology of prediabetes, obesity, and atherosclerosis." (PMID 40806101, 2025). "The results demonstrated that only male SstKO-MSD offspring developed obesity accompanied by severe insulin and leptin resistance after HFD challenge." (PMID 40066865, 2025). "Nutraceuticals such as AX can support metabolic health and physical performance by regulating oxidative stress, inflammation, and mitochondrial function, key processes involved in obesity, insulin resistance, and exercise adaptation." (PMID 41515196, 2025). "In animal models of obesity and diabetes, administration of adiponectin improves hyperglycemia, while its absence leads to reduced insulin sensitivity." (PMID 40522819, 2025). "In the adipose tissue (AT) of individuals with obesity, n-3 PUFAs counteract hypoxia, inhibit immune cell infiltration and AT inflammation, improve insulin sensitivity, and reduce fat mass." (PMID 40219010, 2025). "Such disruption of insulin signaling results in the expansion of fat mass, obesity, and reduced insulin sensitivity, which directly contribute to IR and hyperglycemia." (PMID 40869259, 2025). "Specifically, the Matsuda index was significantly higher in the MHO group (4.43 ± 2.75) compared to the MUO group (2.48 ± 1.61), suggesting preserved insulin sensitivity despite obesity in individuals with MHO." (PMID 39857881, 2025). "In contrast, several studies have reported higher circulating irisin levels in people with obesity and increased irisin secretion by insulin-resistant human myotubes." (PMID 40171198, 2025). "Nurses also recognise the potential of eHealth, anti‐obesity medication, and novel insulin pumps to support lifestyle changes." (PMID 40223769, 2025).
Obesity (continued). "provides functional evidence that under obesity, IRMs directly impair insulin vesicle release through contact-dependent phagocytosis." (PMID 40791590, 2025). "This inflammatory state interferes with insulin function, establishing a connection between obesity and IR, while initiating endothelial dysfunction and the early stages of atherosclerosis." (PMID 40310144, 2025). "At the same time, expanding visceral fat releases fatty acids and inflammatory cytokines that further impair insulin signaling in the liver and muscle, creating a vicious cycle where obesity and IR reinforce each other." (PMID 40959347, 2025). "CB2R also influences obesity, primarily through its role in modulating inflammation and insulin sensitivity." (PMID 39941074, 2025). "In the subgroup with MetS alone, metformin improved insulin sensitivity and modestly reduced weight—effects that align with previous studies emphasizing its utility in managing hyperinsulinemia and obesity in normoglycemic individuals." (PMID 41050568, 2025). "Understanding this interplay between insulin, leptin, obesity and thyroid hormones highlights the importance of managing both obesity and thyroid function to break the cycle of metabolic and endocrine disruptions." (PMID 39857741, 2025). "MicroRNAs are critical post-transcriptional regulators of gene expression influencing multiple cellular pathways, including adipogenesis, insulin signaling, lipid metabolism and chronic inflammation in the context of obesity and metabolic dysfunction." (PMID 41228448, 2025). "Paradoxically, increased insulin sensitivity despite obesity is described for a cohort of people with LS and is thought to protect against the development of diabetes." (PMID 41125144, 2025). "In metabolic regulation, chemerin influences adipocyte differentiation, glucose homeostasis, and central appetite control, connecting obesity with systemic inflammation and insulin resistance." (PMID 41457200, 2025). "At baseline, subjects with obesity had lower insulin sensitivity and elevated plasma LDL-C concentrations." (PMID 40666326, 2025). "NAC enhances metabolic parameters such as obesity, dyslipidemia, blood glucose, and insulin levels, as evidenced by the studies of Sohouli, Mohammad Hassan, and Liu, Jiajun." (PMID 40430469, 2025). "In our study, insulin and leptin levels showed significant improvements in patients with obesity treated with submaximal dosages of GLP-1RA." (PMID 41011232, 2025). "Some found reduced Tregs in obesity and improved insulin sensitivity with Treg induction, while others reported body mass-dependent Treg depletion in adipose tissue." (PMID 39917303, 2025). "Butyrate is the most extensively studied SCFA, with clear beneficial effects on obesity and insulin sensitivity." (PMID 40002674, 2025). "Some studies have indicated a reduction in body mass index (BMI) of 11 to 13 kg/m2 and a decrease in total daily insulin requirements in adult patients with obesity and T1D, with an average change of 0.34 units/kg/day." (PMID 39881371, 2025). "Neutrophils are the first immune cells to accumulate in insulin-sensitive tissues during obesity and they seem to contribute to diet-induced peripheral tissue insulin resistance." (PMID 40670579, 2025). "In obesity, hyperglycemia, and insulin-resistant states, VSMCs undergo phenotypic changes marked by increased proliferation, migration, cell cycle progression, and transformation into inflammatory and osteoblastic phenotypes." (PMID 40940776, 2025). "Mice fed a high-fat diet (HFD), which had limited expression of PTP1B in the hypothalamic region, showed resistance to obesity and enhanced sensitivity to insulin/leptin." (PMID 40356976, 2025). "In the present analyses, consumers of healthy grain foods were less likely to be living with obesity and had lower fasting insulin levels." (PMID 40871702, 2025).
Obesity (continued). "Conversely, participants with long-term obesity showed elevated WC, systolic blood pressure, insulin level, HOMA-IR, and HOMA-β and reduced HDL cholesterol in adulthood." (PMID 40643913, 2025). "For instance, a single intravenous injection of ASCs isolated from C57BL/6 mice was shown to significantly ameliorate obesity, enhance insulin sensitivity, and restore glucose homeostasis in mice with diet-induced obesity." (PMID 40869378, 2025). "When excessive fatty acids accumulate, they form lipid droplets in hepatocytes, which can interfere with insulin signaling, leading to insulin resistance and promoting obesity." (PMID 40867585, 2025). "Visceral fat removal from a mouse model of diet-induced obesity and type 2 diabetes mellitus restored the metabolic parameters and serum cytokine levels, and it attenuated the impairment of insulin signaling." (PMID 40724847, 2025). "Dysfunctional adipose tissue in obesity serves as a source of pro-inflammatory cytokines and adipokines, sustaining chronic inflammation, disrupting insulin signaling pathways, and ultimately impairing glucose homeostasis." (PMID 41008514, 2025). "In our case, normalization of thyroid hormone levels resulted in a significant shift in the growth curve in relation to metabolic syndrome and obesity observed for CS, despite insulin sensitivity." (PMID 40098637, 2025). "In obesity, however, hypertrophic adipocyte expansion induces a state of hypoxia, oxidative stress, and chronic low-grade inflammation, which disrupts insulin signaling." (PMID 41471698, 2025). "Few have investigated how obesity, insulin levels, and vitamin D status interact to influence hyperandrogenism, the main driver of symptom severity." (PMID 40868057, 2025). "In preclinical models, synthetic agonists of REV-ERBs, such as SR9009, exert anti-obesity effects by decreasing adiposity, enhancing insulin sensitivity, and inhibiting hepatic lipogenesis." (PMID 40650041, 2025). "Prolonged adherence to a high-fat diet elevates overall energy intake, fostering obesity and diminishing insulin sensitivity." (PMID 39761309, 2025). "In the context of high‐fat diet‐induced obesity, plakoglobin decreased insulin sensitivity, implicating a potential role in the regulation of glucose homeostasis." (PMID 41451973, 2025). "Numerous studies have shown that probiotic strains, either alone or in combination with other compounds, can exert anti-obesity effects by regulating gut microbiota, enhancing insulin sensitivity, and modulating appetite." (PMID 40635899, 2025). "SCFAs have also been shown to influence appetite regulation, fat storage, and insulin sensitivity, thereby impacting the development and progression of obesity." (PMID 40278284, 2025). "The obvious involvement of IL‐15 in the axis between muscle and adipose tissue plays a key role in improving metabolism by inhibiting obesity and promoting insulin sensitivity." (PMID 39764565, 2025). "For example, activation of MTFP1 in mouse models of obesity and type 2 diabetes was able to significantly improve mitochondrial fusion status, restore insulin sensitivity, and reduce blood glucose levels." (PMID 41030636, 2025). "Growth differentiation factor 15 (GDF15), a cytokine that enhances insulin sensitivity and reduces food intake, is a promising therapeutic target for obesity." (PMID 40530451, 2025). "Despite the high caloric density of honey, accumulating evidence suggests that various types, particularly those derived from Acacia species, exhibit significant anti-obesity, insulin-sensitizing, and hypolipidemic properties." (PMID 40901285, 2025). "After 12 weeks of feeding, mice in the HFD group exhibited significant increases in body weight and body fat percentage, accompanied by impaired glucose tolerance and insulin sensitivity, indicating successful establishment of the obesity model." (PMID 40940715, 2025).
Obesity (continued). "As individuals age, they often experience insufficient insulin secretion, decreased glucose tolerance, and heightened IR due to muscle atrophy, obesity, and osteoporosis." (PMID 40365226, 2025). "This interplay between localized adipose inflammation and systemic metabolic disruption establishes obesity as a chronic inflammatory state with extensive consequences for insulin sensitivity and cardiovascular health." (PMID 40699756, 2025). "In both human obesity and high fat diet-fed rodent models, the increased demand for insulin is compensated for by an increase in β-cell proliferation and functional β-cell mass." (PMID 40134803, 2025). "Significantly increased levels of leptin (68.5 ± 0.35 ng/mL versus 66.73 ± 0.42 ng/mL; p = 0.012) and insulin (98.03 ± 0.54 μIU/mL versus 95.51 ± 0.47 μIU/mL; p = 0.008) suggested a strong resistance to these hormones, typical of monogenic obesity types." (PMID 40428329, 2025). "Muscle loss, particularly in the context of sarcopenic obesity, can further exacerbate metabolic dysfunction, reducing insulin sensitivity and energy expenditure, thereby contributing to the development of obesity." (PMID 40341659, 2025). "Accordingly, we have reason to believe that BBR has an anti-obesity role due to the reversal of insulin resistance of adipocytes." (PMID 39791173, 2025). "It is noteworthy to mention that hyperinsulinemia, in IR and obesity, triggers proliferative tissue anomalies due to the strong anabolic impact of insulin (INS), which stimulates DNA synthesis and cell proliferation." (PMID 41221514, 2025). "Although both insulin and glucagon are anorexigenic in infusion studies, the elevated levels of these hormones in obesity have little effect on appetite." (PMID 41043686, 2025). "Adiponectin, exerts potent anti-inflammatory and insulin-sensitizing effects and is typically downregulated in obesity." (PMID 41463063, 2025). "Second, beyond glycemic control, GLP-1 RA exert metabolic and anti-inflammatory effects—such as weight reduction, improved insulin sensitivity, and lowered systemic inflammation—that are particularly relevant in the context of obesity." (PMID 41502515, 2025). "The effect of obesity on the interplay between insulin, IGF-1, IGF binding proteins and growth hormone is complex and not fully understood, neither in human nor in veterinary medicine." (PMID 40001060, 2025). "Myotubes from insulin-resistant women with extreme obesity show increased MSTN secretion, suggesting that muscle is a source of increased circulating MSTN levels during obesity and T2D." (PMID 40171198, 2025). "IL-17, a key cytokine secreted by γδ T cells in AT, suppresses glucose uptake in skeletal muscle and impairs insulin sensitivity in hepatocytes, positioning γδ T cells as drivers of obesity-related inflammation in T2DM." (PMID 41341586, 2025). "Glucagon, which should be suppressed in the presence of hyperinsulinemia, is also elevated in insulin-resistant individuals with obesity, contributing to the fasting and postprandial hyperglycemia in these individuals." (PMID 41043686, 2025). "The pathophysiological mechanisms underlying obesity in CAH are multifactorial, including supraphysiological glucocorticoid exposure leading to central adiposity, altered insulin sensitivity, and the anabolic effects of chronic hyperandrogenism." (PMID 40564853, 2025). "In the present study, we aimed to evaluate the effect of endurance training on the deleterious effects of obesity including glycemic homeostasis, insulin secretion, and ER stress markers and islet health markers in C57/BL6 mice fed a high-fat diet (HFD)." (PMID 40561274, 2025). "Cluster 3 (blue) consisted of 26 keywords, including obesity, adipose tissue, and insulin sensitivity, suggesting an emphasis on the relationship between obesity and PCOS, particularly how obesity affects metabolism and inflammation." (PMID 41209444, 2025).
Obesity (continued). "Mice with hepatocyte-specific KO of TLR4 (Tlr4LKO) fed a high-fat diet to induce obesity had improved glucose tolerance and insulin sensitivity compared with control mice." (PMID 40985048, 2025). "It has been recently shown that men have poorer antilipolytic effect of insulin compared to women in obesity, and insulin clearance is directly related to body muscle percentage but negatively to body fat percentage." (PMID 40391305, 2025). "Together, these mechanisms adversely affect insulin sensitivity during adipogenesis and lipid metabolism-related genes, contributing significantly to the progression of obesity-related IR and liver steatosis." (PMID 41514930, 2025). "Mazri and colleagues’ study supports this point in an observational study of metabolically healthy versus metabolically unhealthy (higher adiposity, fasting blood glucose, insulin, triglycerides, and blood pressure) individuals with overweight and obesity." (PMID 41305611, 2025). "A meta-analysis pooling the effects of obesity, diabetes, and abnormal glucose and insulin levels found stronger effect size for AD than obesity alone, suggesting that metabolic syndrome as a consequence of obesity might be a stronger risk factor for AD that obesity per se." (PMID 39924587, 2025). "Regarding the interaction of GIP and insulin, even though higher GIP levels are shown to increase insulin secretion and promote satiety, many studies associate GIP levels with obesity." (PMID 40362890, 2025). "In sharp contrast, in obesity, there is a significant reduction in the production of adiponectin, which exhibits anti-inflammatory, cardioprotective, and insulin-sensitivity-enhancing properties." (PMID 39857056, 2025). "A chronic high insulin state (hyperinsulinemia) increases adipogenesis, further exacerbating obesity and MetS." (PMID 39897593, 2025). "Large amounts of evidence in recent years have suggested a crucial role of exosomal miRNAs in various metabolic processes such as glucose and lipid metabolism, insulin signaling, inflammation, and adipogenesis, and are closely related to obesity and T2DM." (PMID 41393285, 2025). "In this study, we provide new lines of evidence to describe how miR-30a expression in adipocytes sustains insulin sensitivity in mice with diet-induced obesity." (PMID 40471675, 2025). "The biological relationship between obesity and cancer is complex, involving several potential mechanisms such as alterations in insulin metabolism, inflammatory responses and steroid metabolism." (PMID 40375215, 2025). "Skeletal muscle plays a key role in obesity-related metabolic disorders, as it is the primary site for insulin-stimulated glucose uptake, accounting for 80% of postprandial glucose clearance from the bloodstream." (PMID 40451926, 2025). "Obesity is one of the major stressors for the β-cell function, where β-cells try to meet the insulin demand due to the concomitant development of insulin resistance (IR)." (PMID 41278909, 2025). "While mice were fed with HFD, lncRNA29RIK KO mice showed marked resistance to HFD-induced obesity, including less body weight and weight of fat-pad tissues, increased sensitivity to insulin, and tolerance to glucose." (PMID 40356927, 2025). "High-fat diet, obesity, insulin, and reactive oxygen species suppress peroxisomal activity, consistent with our findings of reduced ratios of DHA/Total ω3 ratio in milk of subjects with OW/OB." (PMID 40647263, 2025). "In contrast, the MUO phenotype had substantially higher HOMA‐IR values, irrespective of gender, supporting the idea that metabolic disturbances in the context of obesity lead to decreased insulin sensitivity." (PMID 40575865, 2025). "A. muciniphila affects obesity by regulating metabolism and energy balance while also improving insulin sensitivity and glucose control." (PMID 41163054, 2025).